SERPING1 (serpin family G member 1)
Diseases named in the same sentence as SERPING1 in open-access papers (continued):
Sharing a sentence is not in itself a finding about the gene and the disease.
acute monocytic leukemia (1 paper, 2025). Acute monoblastic leukemia (AML-M5), is one of the most common subtypes of acute myeloid leukemia (AML) that is either comprised of more than 80% of monoblasts (AML-M5a) or 30-80% monoblasts with (pro)monocytic differentiation (AML-M5b). "Given the pivotal role of macrophages in the immune responses to both T2DM and TB, we employed a human acute monocytic leukemia cell (THP-1) model to investigate the regulatory effects of the cross-talk genes CHPT1, SERPING1, and CYP1B1 in inflammatory responses." (PMID 40917351, 2025).
Antibody Deficiencies (1 paper, 2023). "The SERPING1 gene-disease relationship was curated by the Antibody Deficiencies GCEP (SERPING1 curation results (clinicalgenome.org)) prior to the initiation of the HAE VCEP’s variant curation." (PMID 38124188, 2023).
babesiosis (1 paper, 2023). Babesiosis refers to a condition caused by microscopic parasites that infect the red blood cells. "Other identified proteins that differentiated uncomplicated from complicated babesiosis were various complement cascade components (CFI, CFP, C2, SERPING1, C8G), extracellular matrix components (TGFBI), acute phase proteins (ORM1, ITIH2, ITIH4, FGA, TF, RBP4) and lipoproteins (apoE)." (PMID 37353646, 2023).
cardiac hypertrophy (1 paper, 2020). "The sets include functions such as PI3K and MAPK kinase signaling pathways, involved in HF-related cardiac hypertrophy, or fibrinolysis and coagulation processes (e.g. FGB, SERPINE1 or SERPING1) and growth factors (e.g. FGF1 or PDGF) related to MD induction." (PMID 32053711, 2020).
cervical cancer (1 paper, 2015). A primary or metastatic malignant neoplasm involving the cervix. "A previous study used DNA microarray data to identify novel candidate molecular markers for cervical cancer diagnosis and therapy, and observed the downregulation of human C1 inhibitor (SERPING1) in invasive cervical carcinoma cells." (PMID 25695263, 2015).
cholangiocarcinoma (1 paper, 2025). A carcinoma that arises from the intrahepatic biliary tree (intrahepatic cholangiocarcinoma) or from the junction, or adjacent to the junction, of the right and left hepatic ducts (hilar cholangiocarcinoma). "For example, distinct peptide mass fingerprints (PMFs) were identified for early versus late recurrence in cholangiocarcinoma (CCA), where peptides such as KNTC1, DCLK1, ALG10, ATR, and BLM were associated with early recurrence, while SERPINA1, TGFB2, and SERPING1 were implicated in late recurrence." (PMID 41008874, 2025).
chronic rhinosinusitis (1 paper, 2020). Chronic form of sinusitis. "In addition, analyses of serpins in matched tissue and mucus exosomal proteins in chronic rhinosinusitis tissue demonstrated upregulated PAI-1 and PAI-2 along with downregulated SERPING1." (PMID 32024545, 2020).
Cirrhosis (1 paper, 2025). A chronic disorder of the liver in which liver tissue becomes scarred and is partially replaced by regenerative nodules and fibrotic tissue resulting in loss of liver function. "Univariate analysis revealed that cirrhosis (p = 0.009), serum AFP (p = 0.011), tumor size (p = 0.001), CLIP score (p < 0.001), AJCC stage (p < 0.001), and high SERPING1 levels (p = 0.011) were significant predictors of improved overall survival." (PMID 39474998, 2025).
endometritis (1 paper, 2024). An acute or chronic, usually bacterial infectious process affecting the endometrium. "Four proteins (apolipoprotein C-II; serpin family G member 1; protection of telomeres protein 1; non-specific serine/threonine protein kinase) were found to be differentially abundant in mares resistant to endometritis in the VIP score (α > 1.5) and in the t-test (p < 0.05)." (PMID 39061562, 2024).
hyperopia (1 paper, 2017). A refractive error in which rays of light entering the eye parallel to the optic axis are brought to a focus behind the retina, as a result of the eyeball being too short from front to back. "A diverse range of complement-related genes were differentially-expressed, with components and regulators of both the classical and alternate pathways up-regulated in late myopia (CS1, PROS1, C1QB and CFD) and late hyperopia (SERPING1, C1QA, CRP, C7 and CFD)." (PMID 28852117, 2017).
inflammatory bowel disease (1 paper, 2025). A spectrum of small and large bowel inflammatory diseases of unknown etiology. "Research has indicated that in the context of inflammatory bowel disease (IBD), the expression of the SERPING1 gene is upregulated, potentially correlating with the exacerbation of intestinal inflammatory responses." (PMID 40433377, 2025).
Insulin resistance (1 paper, 2022). Increased resistance towards insulin, that is, diminished effectiveness of insulin in reducing blood glucose levels. "In some existing proteomics studies, SERPING1 was associated with insulin resistance." (PMID 35433838, 2022).
macular degeneration (1 paper, 2018). Loss of vision in the central portion of the retina (macula), secondary to retinal degeneration. "SERPING1 modulates the complement cascade and is important in many inflammatory diseases, including macular degeneration." (PMID 29992704, 2018).
neuroblastoma (1 paper, 2025). Neuroblastoma (NB) is the most common solid, extracranial childhood tumor. "Its knockdown increases H4K8la levels and induces the transcription of the serpin family G member 1 (SERPING1) and transient receptor potential cation channel, subfamily V, member 4 (TRPV4) genes, which promotes the proliferation and migration of neuroblastoma cells." (PMID 40589733, 2025).
osteoarthritis (1 paper, 2025). A noninflammatory degenerative joint disease occurring chiefly in older persons, characterized by degeneration of the articular cartilage, hypertrophy of bone at the margins and changes in the synovial membrane. "Upregulated gene predicted to be secreted proteins exclusive to 2′3′-cGAMP activation show efficacy in reducing osteoarthritis or enhancing cartilage formation (ITGBL1, Notum, serpinG1)." (PMID 40861855, 2025).
psoriatic arthritis (1 paper, 2024). Joint inflammation associated with psoriasis. "SerpinA12 and SerpinG1 are significantly elevated in the serum of patients with psoriatic arthritis, but their specific mechanism of action in psoriatic arthritis has not been reported." (PMID 39737188, 2024). "SerpinA12 and SerpinG1 is significantly elevated in the serum of patients with psoriatic arthritis, but its specific mechanism of action in psoriatic arthritis has not been reported." (PMID 39737188, 2024).
renal dysfunction (1 paper, 2020). "Except for SerpinG1 in LDL sub‐fraction, which was associated with decreased risk of renal dysfunction, no other significant associations were found." (PMID 32648717, 2020). "Given the relevance of renal dysfunction, inflammation, and the coagulation system in the development of cardiovascular diseases, we extended previous work on Cystatin C, CD14, SerpinG1, and SerpinF2 within circulating EVs to explore their possible associations with the CRS." (PMID 32648717, 2020).
restless legs syndrome (1 paper, 2024). A condition that occurs while resting or lying in bed; it is characterized by an irresistible urgency to move the legs to obtain relief from a strange and uncomfortable sensation in the legs. "In addition, SERPING1 protein levels were reduced in the blood of patients with restless legs syndrome." (PMID 39835101, 2024).
type 2 diabetes (1 paper, 2016). "Eight haplotype-tagging SNPs of SERPING1 and C5 were genotyped in 570 subjects with type 2 diabetes: 295 DR patients (138 nonproliferative DR [NPDR] and 157 proliferative DR [PDR]) and 275 diabetic controls." (PMID 26989329, 2016).
genetic disorder (42 papers, 2008 to 2026). "HAE is a rare hereditary disease primarily attributed to abnormal C1-INH concentration or function resulting from genetic variation in the SERPING1 gene." (PMID 39272138, 2024).
tumor (32 papers, 1989 to 2025). "In our quest to unravel the impact of SERPING1 on the prognosis of LUAD patients, we observed a declining trend in SERPING1 levels corresponding to tumor size increments from T1 to T3 and T4." (PMID 39962118, 2025). "Among these, 16 tumor tissues exhibited lower SERPING1 expression compared to corresponding normal tissues (left)." (PMID 39474998, 2025). "Noteworthy differences were observed in SERPING1 levels, with tumor cells exhibiting lower expression compared to ciliated and secretory cells based on scRNA-seq." (PMID 39962118, 2025). "The role of SERPING1‐mediated classical pathway activation in either facilitating tumour cell eradication or enhancing tumour proliferation in HCC remains ambiguous." (PMID 39853609, 2025). "Results indicated a strong correlation between SERPING1 overexpression and tumor proliferation, encompassing pathways such as the tumor necrosis factor (TNF) signaling pathway, cell cycle and DNA replication." (PMID 39962118, 2025). "Quantitative analysis of IHC staining scores revealed that SERPING1 expression was significantly downregulated in tumor tissues compared to normal controls (right)." (PMID 39474998, 2025). "Cumulatively, the data converge to spotlight SERPING1 as a novel tumor suppressor gene in the context of LUAD." (PMID 39962118, 2025). "SERPING1 is a previously proposed biomarker candidate for stratification of HGSC with its elevated levels in tumor fluids compared to fluids from B tissue." (PMID 40778374, 2025). "In summary, SERPING1 emerges as a novel tumor suppressor gene and SP5/SERPING1/TSC2 is a promising therapeutic target in the context of LUAD." (PMID 39962118, 2025). "To validate the tumor-suppressing effects of SERPING1 in vivo, we executed a nude mouse xenograft model." (PMID 39962118, 2025). "Additionally, both in vitro and in vivo experiments were undertaken to validate the tumor-suppressing capabilities of SERPING1 specifically and regulation of TSC2/mTOR pathway in LUAD." (PMID 39962118, 2025). "Given the pro-tumor roles of the C1Q complex, we hypothesized that the C1Q inhibitor SERPING1 may inhibit tumor progression." (PMID 41473324, 2025). "Consequently, SERPING1 expression was significantly decreased with higher AFP levels, predicted metastasis risk signature, primary tumor size, and more advanced pathological stage of HCC." (PMID 39474998, 2025). "This discovery indicates that SERPING1 may regulate the tumour microenvironment by affecting macrophage polarisation." (PMID 39853609, 2025). "Notably, the most dysregulated gene, AHNAK nucleoprotein 2 (AHNAK2), exhibited increased levels during tumor cell development in the control scenario, while SERPING1 expression decreased during the later stages of pseudotime." (PMID 39962118, 2025). "A plausible regulatory mechanism we identified suggests that decreased SERPING1 expression in tumor cells might hyperactivate the classical complement pathway, thereby promoting lung carcinogenesis and progression." (PMID 39962118, 2025). "Notably, we noted a decrease in SERPING1 levels within tumor regions." (PMID 39962118, 2025). "Notably, immune checkpoint inhibitors stimulate cytotoxic T cell proliferation, while SERPING1 overexpression diminishes Myeloid-Derived Suppressor Cells (MDSCs) infiltration in the tumor microenvironment, alleviates MDSC-induced T cell suppression, and enhances overall T cell function." (PMID 39962118, 2025). "Based on the evidence, we suggest that SERPING1 might be a tumor suppressor in HCC progression." (PMID 39474998, 2025). "We found that high SERPING1 expression was significantly associated with better overall survival and recurrence‐free survival rates, and SERPING1 expression was decreased in late‐stage HCC tissues compared with early‐stage HCC tissues, which indicates that SERPING1 might be a tumor suppressor." (PMID 39474998, 2025).
tumor (continued). "We conducted a more in‐depth examination of the functions of SERPING1 and STEAP3 inside the tumour microenvironment of HCC." (PMID 39853609, 2025). "The findings indicated that SERPING1 and STEAP3 were aberrantly regulated in the majority of tumours." (PMID 39853609, 2025). "We also found that ARL4C and HOXC8 were upregulated, and FABP4, PCOLCE2, SERPING1, and SRPX were downregulated in tumor tissue compared to corresponding healthy tissue." (PMID 35664768, 2022). "And the Pearson correlation coefficients between NNMT and CRYZ, and SERPING1 and ANGPTL4 across all TCGA tumor samples were 0.4, 0.43, and 0.62, respectively." (PMID 36386816, 2022). "On the other hand, gene expression analyses confirmed that proteins related to the complement activation, such as C1QA, SERPING1, A2M, ITGAM and ITGB2, were significantly overexpressed in P3 tumours, compared to P1 and P2 subtypes." (PMID 31560832, 2019). "For example, some known oncogenes, such as KMT2B and TERT, were dominantly observed in tumor while fusion transcripts with CYP3A5, SERPING1, and WDR72 were only found in normal tissue." (PMID 29212479, 2017). "Notably, SERPING1 expression exhibited significant correlations with serum AFP (p < 0.001), tumor size (p = 0.047), and CLIP score (p = 0.002)." (PMID 39474998, 2025). "In the B16F10 cell line, which is less immunogenic, the Serping1 overexpression also slowed tumor growth, albeit not to a level of statistical significance (p = 0.214)." (PMID 41473324, 2025). "SERPING1 and STEAP3 affect tumour cells and modify the tumour microenvironment (TME), indicating that targeting these genes may offer a viable immunotherapeutic approach for HCC in clinical settings." (PMID 39853609, 2025). "Moreover, in terms of recurrence‐free survival, univariate analysis identified tumor size (p = 0.045), CLIP score (p = 0.002), AJCC stage (p < 0.001), and high SERPING1 levels (p = 0.026) as significant predictors of better outcomes." (PMID 39474998, 2025). "Notably, five DEG expression levels were correlated with prognosis in these three tumor types, including AXL, CCDC152, EVI2B, GLIPR1, and SERPING1." (PMID 32903590, 2020). "In previous studies, TaqMan quantitative PCR was utilized to confirm the expression of several genes (decorin, IGFBP2, Thrsp, Sncg, SerpinG1) in MIN-O and tumor pairs and showed that this data correlated with the direction and fold change of the microarray data." (PMID 17147824, 2006).
infection (28 papers, 2009 to 2025). The state of being infected such as from the introduction of a foreign agent such as serum, vaccine, antigenic substance or organism. "Correlations between PRRs and transcripts related to thrombosis and coagulation identified three transcripts having the highest associations with PRRs across all three infections: PLAUR, SERPING1, and SELPLG." (PMID 40825056, 2025). "In the exploration of potential signaling pathways influenced by SERPING1, we conducted RNA-seq on A549 cells following infection with control and lentivirus to induce SERPING1 expression." (PMID 39962118, 2025). "Expression levels of alpha-2-macroglobulin-like (A2M), decay accelerating factor (DAF), and minus strand C1 inhibitor (SERPING1) were unaffected by infection." (PMID 25496447, 2014). "SERPING1 levels were knocked down through siRNA infection, and elevated via plasmid transfection." (PMID 39962118, 2025). "The ensuing accelerated downregulation of Serping1 may, in turn, reflect that less C1INH is required, or may even be a hindrance, during this period of infection, whereas C1INH is required again for the final recovery from infection." (PMID 40243929, 2025). "Common associations were observed across all three infections which most frequently involved PLAUR and SERPING1, suggesting that common pathways linking acute respiratory infection to thrombosis may involve these gene transcripts." (PMID 40825056, 2025). "Similarly, the activation of genes such as Serping1, Sparc, Pcsk5, Fgf7, and Cyp7b1 indicated the temporal activation of cell migration and immune suppression during infection." (PMID 38767331, 2024). "Moreover, C3, C5, C2, C1S, C4BPA (genes involved in the complement pathway) and SERPING1 (a regulator of complement activation) were significantly up-regulated, indicating an important role of the complement pathway in this infection." (PMID 34203742, 2021). "Interestingly, the protein encoded by SERPING1 is associated with regulatory inhibition of the complement system and may be upregulated in CD14 + monocytes from PLWH as a mechanism of limiting infection." (PMID 41345807, 2025). "The gene transcripts with the greatest number of shared correlations with PRRs across all three infections were PLAUR (with TLR2, RIG-I, LGP2) and SERPING1 (with TLR5, RIG-I, MDA5, and LGP2)." (PMID 40825056, 2025). "In contrast, PbA infection-induced ECM controls (Pb group) demonstrated a significant increase in GFAP+ (P < 0.01) and Serping1+ (P < 0.01) astrocytes compared with uninfected mice." (PMID 41214704, 2025). "In the current study, three SERPINs were differentially expressed following infection; SERPINA1 (α1–antitrypsin), SERPIND1 (heparin coagulation factor II) and SERPING1 (C1-inhibitor; C1INH)." (PMID 36088326, 2022). "SerpinG1 protein expression was greatly reduced in renal tissues from mice receiving AAV9-sh.SerpinG1 delivery, whose infection efficiency in renal tubular epithelial cells was equivalent to AAV9-Scr delivery." (PMID 35982894, 2022). "Other DEGs of note that were upregulated throughout infection include the monocyte chemoattractant CXCL10 (C-X-C Motif Chemokine Ligand 10) and the C1 inhibitor SERPING1 (Serpin Family G Member 1)." (PMID 29123522, 2017). "However, within cluster B, SERPING1 shows a significant negative correlation with the infection intensity." (PMID 36088326, 2022).
autosomal dominant disease (25 papers, 2013 to 2025). Autosomal dominant form of disease. "HAE is an autosomal dominant disease and patients are heterozygous for the defected SERPING1 allele." (PMID 37470035, 2023). "HAE type 1 (HAE-1) and type 2 (HAE-2) are usually autosomal dominant diseases caused by mutations in the C1 inhibitor (C1-INH) gene SERPING1." (PMID 33292549, 2020). "HAE is an autosomal dominant disease caused by a deficiency of functional C1 inhibitor, due to a mutation in C1-INH gene (serping 1 gene) characterized by the clonal proliferation of mast cells, leading to their accumulation, and possibly mediator release, in one or more organs." (PMID 25674297, 2015). "HAE is an autosomal dominant disease caused by a deficiency of functional C1 inhibitor (C1-INH), due to a mutation in C1-INH gene (serping 1 gene) mapped to chromosome 11(11q12-q 13.1)." (PMID 25674297, 2015).